HIF1A (hypoxia inducible factor 1 subunit alpha)
Diseases named in the same sentence as HIF1A in open-access papers (continued):
Sharing a sentence is not in itself a finding about the gene and the disease.
tumor (continued). "BHLHE40 is activated under hypoxic conditions by HIF-1α in HCC, stimulating tumour progression." (PMID 35109839, 2022). "Increased TGF-βRII expression correlates with PKM2 and HIF-1α, so it is possible that TGF-βRII might regulate glycolysis in oral CAFs, leading to affect the tumor progression in OSCC." (PMID 35013150, 2022). "The expression of HIF-1α may decrease immediately after cTACE and remain undetectable several weeks after TACE along with the onset and increasing extent of tumor necrosis." (PMID 35619923, 2022). "Represented by IL-1 and IL-6, primary mediators of GBM tumor cells in the inflammatory TME can orchestrate immunological activation and inflammatory signaling cascades such as hypoxia-inducible factor-1α (HIF-1α), Wnt-1, nuclear factor-kappa B (NF-κB), and STAT3 in GBM." (PMID 35572545, 2022). "M2 phenotypic markers, such as CCL22, HIF-1a, Ym1, and MMP-9, which are involved in immunosuppression, angiogenesis, epithelial–mesenchymal transition, and invasion, were significantly upregulated by tumor challenge compared to the WT group." (PMID 35216272, 2022). "Moreover, NF-κB is also reported to repress E-cadherin and activate ZEB1 protein which are the downstream regulators of HIF-1α pathway indicating that NF-κB and HIF-1α both depends on each other to induce EMT in tumor." (PMID 36014432, 2022). "In addition, immunohistochemical analysis showed that the expression of SIRT6, HIF-1α, HK2 and Ki-67 in tumor tissues of the PC9/SIRT6 group was higher than that of the PC9/vector group." (PMID 35915188, 2022). "Contrary to HIF-1α which is a ccRCC suppressor, HIF-2α is a ccRCC oncoprotein and therefore an interesting therapeutic target already evaluated in several phase 2 that showed anti-tumour activity." (PMID 36551652, 2022). "Ectopic expression of HIF-2α, but not HIF-1α increased cytotoxic, differentiation and cytolytic function against tumor targets of CD8 T cells." (PMID 36064840, 2022). "Furthermore, the dissociation-related genes FOS, FUN, and HIF1A, were all expressed on the formalin-fixed paraffin-embedded (FFPE) tumor samples." (PMID 36008393, 2022). "In tumor tissues, TGF-β is reportedly regulated, in part, by HIF1α, HIF2α, miRs-155, and miR-210." (PMID 35628416, 2022). "Moreover, GBM tumor cells together with GAMs generate a mass of succinate and lactate through the PI3K/HIF-1α pathway, thus aggravating local inflammation and GBM metastasis." (PMID 35572545, 2022). "TNF-α and IL-17 synergistically enhance glycolysis and lactate production in CRC HT-29 cells via activation of the NF-κB axis in tumor cells, and they promote GLUT1 and hexokinase 2 (HK2), as well as expression of the common target genes HIF-1α and c-myc which, in turn, promote tumorigenesis." (PMID 36588722, 2022). "The benefit from radiotherapy was similar in patients with HIF-1α-positive and -negative primary tumours." (PMID 35140341, 2022). "Furthermore, hypoxia‐induced HIF‐1α can increase the expression of metalloproteinase ADAM10, which regulates the shedding of the MHC‐I‐chain related molecule A (MICA) from the tumour cell surface." (PMID 35466515, 2022). "From the immunofluorescence analysis of tumour sections stained with TUNEL and HIF-1α, one can see that PLT/CANS treatment could conquer tumour hypoxia." (PMID 36277398, 2022). "Thus, in normal conditions, SETD7 targets HIF-1α for degradation operating as a tumour suppressor, but in oxidative stress, SETD7 exerts tumour-promoting effects by maintaining redox homeostasis to protect cancer cells from apoptosis." (PMID 35326563, 2022). "Since HIF-1α is the gold standard for identifying hypoxia, this result suggests that ANGPTL4 may also be a conspicuous molecule distinguishing hypoxic tumour cells from normoxic cells." (PMID 36050447, 2022).
tumor (continued). "In addition to affecting immune effector function, hypoxia, plus continuous tumor antigen stimulation, can also induce expressions of exhaustion markers TIM-3 and TIGIT, which is HIF1α-independent." (PMID 35840558, 2022). "For instance, in a mouse melanoma model HIF-1α-/- CD8+ T cells show decreased expression of soluble factors including TNFα, IFNγ and granzyme B and tumor infiltration under hypoxia correlating with increased tumor growth." (PMID 35769460, 2022). "HIF-1α could directly upregulate ANGPTL4 and promoted tumour metastasis by activating the vascular cell adhesion molecule-1/integrin β1 signalling axis." (PMID 36050447, 2022). "Additionally, S1P can also activate HIF-1a, resulting in the production of VEGF and pro-tumour cytokines such as IL10 and IL6." (PMID 36497148, 2022). "Research evidence has also shown that hypoxia could induce the HIF-1α/G-protein estrogen receptor (GPER) in CAFs, which regulates VEGF and finally elicit hypoxia-dependent tumor angiogenesis." (PMID 36532768, 2022). "Moreover, nuclear cooperative translocation of HIF-1α and p-STAT3 has been observed in the tumor microenvironment." (PMID 36496973, 2022). "We demonstrated that Pramlintide therapy resulted in decreased HIF-1α in the TME, again suggesting that Pramlintide can help alter the TME from one that is immunosuppressive to one that supports immune cell mediated anti-tumor activity." (PMID 36077845, 2022). "Furthermore, hypoxia and overexpression of hypoxia-inducible factors (HIFs) 1 and 2 alpha (HIF1A and HIF2A) are involved in tumor immune escape and promote tumorigenesis." (PMID 35659268, 2022). "Therefore, in tumour tissues under hypoxic conditions, activation of the PI3K/Akt/mTOR pathway promoted the expression of Glut‐1 and HIF‐1α." (PMID 35415942, 2022). "In lung cancer models, SIRT-6 overexpression may decrease HIF-1α and VEGF expression and promote prolyl hydroxylase-2 expression, thereby inhibiting angiogenesis and tumor growth." (PMID 35906622, 2022). "Lactate is taken up by tumor cells in well-oxygenated areas, which are HIF1α-negative and express the MCT1 transporter." (PMID 35053485, 2022). "Overexpression of HIF1A promotes production of CD24, which leads to tumor growth and metastasis." (PMID 35659268, 2022). "Lactate accumulation allows tumor cells to activate the expression of procarcinogenic genes due to the transcriptional activity of HIF-1α, regardless of oxygen supply." (PMID 36230479, 2022). "HIF-1α expression is often accompanied by the activation of its downstream factor GLUT-1, which makes cancer cells survive in the hypoxic environment, and is related to aggressive tumor behavior." (PMID 35800058, 2022). "The reader YTHDF1 promotes tumor progress by influencing ATG2A, ATG14, and HIF-1α." (PMID 36059442, 2022). "It has been reported that TLR3 could induce the expression of the I.3 isoform of HIF-1α, which accumulates in the nucleus even in normoxia, promoting the secretion of VEGF and tumor progression in prostate cancer." (PMID 35565420, 2022). "HIF-1α and HIF-2α silencing in TNBC xenografts significantly reduced tumor growth." (PMID 36012111, 2022). "Furthermore, both PX-478 and EZN2968 elicit dose-dependent decreases in HIF-1α levels and VEGF expression, as well as the tumor size in DU145 xenograft models, and both small-molecule inhibitors were well tolerated in clinical activities." (PMID 35205167, 2022). "The length showed no significant changes in the Hif1α knockdown tumor compared with that in the control." (PMID 35695994, 2022). "In contrast, homoplasmic MT‐ND1 mutations conferring a milder effect on complex I activity (m.3460G>A/MT‐ND1) did not induce HIF1α destabilization or inhibit tumour growth." (PMID 35842901, 2022). "Dividing the patients into those with HIF-1α negative and positive primary tumours, there was a similar reduction in IBTR with RT in the two groups (test for interaction yearsp = 0.90, test for interactionfull FUp = 0.66)." (PMID 35140341, 2022).
tumor (continued). "Importantly, the functional studies showed that the tumour-suppression role of SETD7 is related to its methylation of oncogenic target proteins (Dnmt1, E2F-1 and HIF-1α) leading to their degradation." (PMID 35326563, 2022). "In a mouse tumor xenograft model bearing SKOV3 cells, OPLMBs followed by US mediation resulted in enhanced oxygen and anti-cancer drug delivery to tumors with consequent decreases in tumor tissue, angiogenesis, and HIF-1α and P-gp expression." (PMID 36132133, 2022). "Regardless of at hypoxia or at normoxia, tanshinone I subdued angiogenesis in epithelial cells (HMEC-1) and the secretion of VEGF from tumor cells (MCF-7) by the common mechanism: deduction of p-STAT3 and HIF-1α, and also inhibited VEGF against lung carcino-angiogenesis." (PMID 35784750, 2022). "Moreover, in hypoxia, the HIF-1α-induced expression of inducible NOS (iNOS) further increases NO concentration, which contributes to tumor progression by promoting the neovascularization of tumor masses." (PMID 36551540, 2022). "While targeting HIF-1α has shown some success, it fails to address the oncogenic biochemical pathways involved in tumor progression that are reliant on HIF-2α, as previously discussed." (PMID 35267567, 2022). "However, the biology of the protein is unclear, with early evidence linking HIF-1α mediated EMT in hypoxia and the PI3K/AKT/mTOR pathway with AHNAK2 as possible modes to increase tumour proliferation, migration, and survival." (PMID 35158796, 2022). "Subsequently, the activated HIF-1α will translocate into the nucleus and form a heterodimer with HIF-1β to transactivate the transcription of target genes involved in tumor survival, metastasis, and angiogenesis, including vascular endothelial growth factor (VEGF)." (PMID 36080483, 2022). "YC-1 is a targeted HIF-1α inhibitor, which can resist intravascular thrombosis, block the hypoxia signaling pathway of cells, inhibit the expressions of HIF-1α and VEGF, inhibit tumor angiogenesis, and tumor cell proliferation, thereby exerting anti-tumor and anti-angiogenic effects." (PMID 35684364, 2022). "Likewise, cooperation of HIF-1α and SP1-mediated CD147 led to increased glycolysis and tumor progression in epithelial solid tumors." (PMID 35590288, 2022). "We show here that HIF2α protein is preferentially accumulated in tumor cells of SDH-mutated PPGL, but HIF1α is not." (PMID 35740651, 2022). "In hypoxic condition, the complex of HIF-1α and HIF-1β mediates an adaptive transcriptional response to hypoxia, including glycolytic metabolism activation, pro-angiogenic factor secretion, genetic instability in tumor cells, and increased cell migration." (PMID 35448036, 2022). "For example, HIF-1α induces the expression of lincRNA-p21 under hypoxic conditions, and lincRNA-p21 can prevent the direct binding of HIF-1α with VHL and maintain the stability of HIF-1α, thus promote tumor survival by increasing the level of intracellular glycolysis." (PMID 35387966, 2022). "HIF-1α downregulation also decreased the expression of glucose transporter 1 (GLUT1) and lactate dehydrogenase A (LAHA) which can impair aerobic glycolysis of tumor cells." (PMID 35527284, 2022). "Other authors, in turn, have not observed differences in HIF1A expression and demonstrated similar cytoplasmic protein content in early and advanced tumor stages." (PMID 36230822, 2022). "HIF1A is considered the most significant regulator of hypoxic response in GBM, and it interacts and co-operates in a significant way with both UPS and autophagy for tumor growth." (PMID 36552827, 2022). "HIF-1α and GLUT-1 were expressed by tumor cells in nearly all 28 cytological cases." (PMID 36620569, 2022). "Under hypoxic states, IL-6 promotes hypoxia-inducible factor 1α (HIF-1α, HIF1A) and signal transducer and activator of transcription-3 (STAT-3) transcription, which stimulates VEGF expression, blood vessel formation, and tumor growth through defective angiogenesis." (PMID 36432658, 2022).
tumor (continued). "ALK regulated VEGFA production and tumor angiogenesis in NSCLC, dependent on both HIF1α and HIF2α." (PMID 36012123, 2022). "Collectively, these findings suggest that both HIF-1α and HIF-2α contribute to tumor angiogenesis." (PMID 35805939, 2022). "Links among hypoxia, HIF-1α, E-cadherin, angiogenesis and EMT are shown to promote tumor invasion." (PMID 36467998, 2022). "Microbead-induced increases in tumor burden were absent, however, in both myeloid HIF1α KO mice and myeloid HIF2α KO mice." (PMID 36291563, 2022). "Finally, we confirmed the physical interactions of Ifi204, HIF1α, and PRMT2 in the tumor tissues using PLA." (PMID 35593921, 2022). "What’s more, hypoxia-inducible factor-1α (HIF-1α) is a key transcriptional regulatory protein that regulates an arrangement of hypoxia-sensitive proteins expression, such as PKM2, HK2, PFKP, to preserve the survival of tissue in tumor microenvironment." (PMID 36536346, 2022). "Moreover, estrogenic signaling via GPER activates the HIF-1α/VEGF transduction pathway leading to angiogenesis and tumor growth." (PMID 35740412, 2022). "As a key point to tumor anabolism, mTOR is mainly activated by phosphatidylinositol-3 kinase/protein kinase B/mammalian target of rapamycin (PI3K/AKT/mTOR) signal, which also regulates HIF-1α translation." (PMID 35413842, 2022). "HIF-1α promotes EMT in cancer cells by activating the transcription of genes in the LOX family, and induces angiopoietin-like-4 (ANGPTL4), resulting in tumor growth and resistance to anoikis." (PMID 35740397, 2022). "HIF-1α has been shown to bind to transcriptionally active hypoxia-response elements (HRE) in the PD-L1 proximal promotor and to upregulate the expression of PD-L1 on tumor cells and MDSCs." (PMID 35805044, 2022). "Tumor hypoxia drives VSIR expression, which correlates significantly with HIF1A activity." (PMID 35659268, 2022). "As both MGMT and HIF-1α showed negative expression in all the tumor lesions, correlation analysis or difference comparison was not further performed." (PMID 36591483, 2022). "Propofol could inhibit the upregulation of HIF-1α expression and reactive oxygen species (ROS) production in NSCLC tumor cells induced by LPS, suppressing the expression of VEGF, promoting tumor cell apoptosis as well as inhibiting invasion and metastasis." (PMID 36506511, 2022). "For example, expression of HIF-1α, CSC can promote tumor progression and metastasis." (PMID 35659296, 2022). "Despite USP2-AS1 is up-regulated under hypoxia, USP2-AS1 specifically increases the protein level of HIF1α but not HIF2α, suggesting that the molecular mechanisms of hypoxia metabolism in tumor growth are complex and need further research." (PMID 35692750, 2022). "The higher occurrence of IBTR in patients that had HIF-1α positive primary tumours was apparent in both ER-positive and -negative disease." (PMID 35140341, 2022). "HIF-1α solves this problem by upregulating the translocation of glucose transporters (GLUTs), such as GLUT1 and GLUT3, to the cell membrane to facilitate greater glucose influx required for glycolysis into the tumor cells." (PMID 36140753, 2022). "On the other hand, another study demonstrated that HIF1α-/-Ncr1iCreTg NK cells reduced tumor progression not by enhanced cytokine production and anti-tumor activity, but by inducing non-productive angiogenesis of the tumor." (PMID 35769460, 2022). "Additionally, expression of other IRE1α/XBP1s-target genes, including XBP1s, HIF1α, DDIT4, and JMJD1A, was increased in ALDH+ cell–enriched tumor spheroids, suggesting that the UPR pathway was activated in spheroid cultures and in CSCs." (PMID 35349489, 2022). "Immunofluorescence staining assay confirmed that URB localized in the region where the HIF-1α highly expressed, but not in the region where the tumor was not hypoxic." (PMID 35918309, 2022).
tumor (continued). "In addition, novobiocin can down-regulate the expression of genes regulated by HIF-1α, especially CA9, which is related to tumorigenesis, and thus exert an inhibitory effect on tumor cell proliferation." (PMID 36139386, 2022). "Since the pro-proliferation effect of polyamines can increase the oxygen consumption of cells, whether the regulation of HIF1α expression by MYC is related to the upregulation of ODC by MYC and thus increases oxygen consumption by tumor cells." (PMID 35912204, 2022). "The results suggest that HIF1A levels can correlate with CPD100 and CPD100Li efficacy and that HAP testing in organoid cultures can be further developed to personalize therapy based on tumor oxygenation levels." (PMID 35456547, 2022). "Furthermore, green tea catechins suppressed invasion and migration by TIMPs and MMPs; inhibited tumor angiogenesis by downregulating IGF-1, HIF1α and VEGF; and targets NK-κB, COX-2, interleukin family, androgen receptor to suppress prostate cancer cell growth." (PMID 35860020, 2022). "Downregulation of proteins mediating HIF-1α degradation, such as FBXO28, could provide these tumor cells with a further mechanism for this upregulation." (PMID 36115843, 2022). "Piezo1, HIF-1α, and VEGF are highly expressed in tumor tissues." (PMID 36230880, 2022). "In patients with ER-negative tumours, with a high frequency of HIF-1α positive primary tumours (60%), BCD within 10 years was higher compared to ER-positive tumours irrespective of primary tumour HIF-1α status." (PMID 35140341, 2022). "Stabilization of HIF-1α in LUAD promotes glycolysis, thereby enhances tumor metastasis." (PMID 35372052, 2022). "Copper also could trigger the expression of GPER, VEGF, and HIF-1α via activating EGFR/ERK/c-fos transduction pathway, affecting the angiogenesis and tumor progression in BRCA and LIHC." (PMID 36052076, 2022). "Interestingly, induction of CAFs autophagy has been shown to promote tumour cell survival through processes involving the downregulation of CAV-1 and subsequent stabilization of Hypoxia Inducible Factor 1-alpha (HIF1-α)." (PMID 36555218, 2022). "Since tumor cells also express HIF-1α under normoxia, we tested whether the HIF-1α/PD-L1 axis is also active in tumor cells stably expressing HIF-1α under normoxic conditions." (PMID 35239514, 2022). "Furthermore, in vivo studies confirmed that HIFAL overexpression promotes tumor growth, while targeting/inhibiting both HIFAL and HIF-1α significantly reduces cancer growth." (PMID 36182907, 2022). "To investigate whether fisetin inhibited tumor growth through the AKT/HIF-1α signaling pathway, we found that fisetin could significantly reduce the levels of p-AKT, HIF-1α, and VEGF (P < 0.01)." (PMID 35222641, 2022). "Interestingly, HIF-1α is involved in the regulation of P4HA1 and P4HA2 expression in tumor cells and fibroblasts." (PMID 36140753, 2022). "HSP70 also interacts with aminoacyl-transfer RNA synthetase-interacting multifunctional protein 2 (AIMP2) lacking exon 2 (AIMP-DX2) and HIF-1α, leading to angiogenesis, metastasis and tumor aggressiveness." (PMID 35127545, 2022). "Primary tumour HIF-1α positivity was also associated with an increase in BCD, but not when adjusted for patient age, tumour subtype, size and systemic treatment." (PMID 35140341, 2022).